IL1R1 (interleukin 1 receptor type 1)
Diseases named in the same sentence as IL1R1 in open-access papers (continued):
Sharing a sentence is not in itself a finding about the gene and the disease.
infection (163 papers, 2008 to 2026). The state of being infected such as from the introduction of a foreign agent such as serum, vaccine, antigenic substance or organism. "Single-nucleus-RNA-sequencing data implicates excessive metabolic activity and oxidative phosphorylation across all cell types in the kidney of Il1r1-deficient mice within a few hours upon infection, with associated, localized hypoxia at infection foci." (PMID 40097388, 2025). "The stepwise decrease in NO production and the stepwise increase in CFU between B6 BMDMs to Ifnar1-/-and Il1r1-/- BMDMs to DKO BMDMs support the idea that NO production is associated with protection against rpoB-H445Y Mtb infection." (PMID 38603763, 2024). "As expected, Il1r1-/- mice were unable to control wt Mtb infection, with elevated lung burden at 14- and 30-days post-infection (dpi), relative to C57BL/6 (B6) mice, whereas loss of Ifnar1 alone has no impact on Mtb burden." (PMID 38603763, 2024). "The phenotype was reverted by IL-1R1-deficiency, demonstrating that IL-1R8 prevented P. aeruginosa associated inflammation by negatively regulating IL-1R1, the major signaling pathway involved in the pathogenesis of this infection." (PMID 35211118, 2022). "At the site of infection, Il1r1-/- mice sustained increased cortical bone loss in comparison to WT mice." (PMID 30978245, 2019). "To address this issue, we isolated pDCs from YM-infected WT and gene deficient (Aim2−/−, Nlrp3−/−, Casp1−/−, Il1r1−/−, and Mavs−/−) mice at 18 h post YM infection and assessed mRNA expression levels of SOCS1, IFN-α and IFN-β." (PMID 30470758, 2018). "The increased susceptibility of Casp1/11-/-, Asc-/-, and IL-1r1-/- mice to Ft LVS infection in this study and IL-1β-/- mice in a previous study clearly underscore the critical requirement of IL-1β/IL-18 for protective immunity." (PMID 27926940, 2016). "In contrast, 100% of TNF-α mice died or had to be sacrificed within one month post infection and IL-1R1 deficient mice exhibited an intermediate susceptibility with a 50% survival during the 4 months follow-up period (P = 0.0455)." (PMID 25950182, 2015). "Bacterial burden was significantly increased in IL-1R1 deficient mice as compared to WT mice at 1 month (P = 0.0091) and 4 months (P = 0.0193) post-infection." (PMID 25950182, 2015). "In vivo, IL-1R1 deficiency was shown to result in enhanced Th2-type immune responses following infection with the protozoan parasite Leishmania major and IL-1α was reported to promote Th1-biased immune resistance to Leishmania major." (PMID 23935505, 2013). "The levels of IL-17A were also reduced in mice deficient for both IL-1α and/or IL-1β or IL-1R1 at 5 weeks post-infection and in IL-1α or IL-1β single deficient mice at 8 weeks post-infection." (PMID 25400917, 2013). "IL-1α and IL-1β double deficient mice exhibited strongly increased lung weights, an indicator of lung inflammation, 5 weeks post-infection, as did IL-1R1 deficient mice and TNF KO mice which succumbed at 4 weeks." (PMID 25400917, 2013). "However, several studies in mice have shown an increased risk of infection in response to complete blockage of endogenous IL-1β, as well as in studies of IL-1R1-deficient mice." (PMID 35632584, 2022). "IL-1R1 knockout mice exhibited higher susceptibility to infection than wild-type mice." (PMID 31998465, 2019). "TNF deficient mice rapidly lost weight and succumbed by 6 weeks of infection with highly inflammed lung, spleen and liver, while IL-1R1 and IL-1α plus IL-1β deficient mice survived systemic M. bovis BCG infection with lung, spleen and liver weight similar to wild-type mice at 6 and 11 weeks." (PMID 25400917, 2013). "The number of IL-1R1 expressing TFH cells increase between 7 and 10 dpi, with TFH cells expressing significantly higher quantities of IL-1R1 compared to nTFH cells in the mediastinal lymph node (mLN) at days 7, 10, and 15 post infection." (PMID 40825032, 2025).
infection (continued). "To obtain information about the inflammatory state of the Il1r1-/- mice, we analyzed the cytokine and chemokine protein levels in lysates of the kidney and brain of WT and Il1r1-/- mice 2.5 days post-infection (p.i.)." (PMID 40097388, 2025). "We were surprised to see striking transcriptional differences between Il1r1-/- and Il1r1+/- mice so early upon infection." (PMID 40097388, 2025). "To explain the high number of neutrophils seen in Il1r1-/- mice, we infected WT mice with increasing infection doses of C. albicans." (PMID 40097388, 2025). "Visualization of poorly oxygenated areas in histological sections confirmed that the kidneys of Il1r1-/- mice became rapidly hypoxic upon infection." (PMID 40097388, 2025). "Pathway activity analysis with PROGENy database showed reduced activity of a few main pathways upon infection of Il1r1-/- mice, such as NF-κB, Wnt, and PI3K." (PMID 40097388, 2025). "A multitude of genes encoding for subunits of complexes I, III, IV, and V of the electron transport chain (ETC) were up in all kidney cells within 8 h after infection of Il1r1-/- mice compared to controls." (PMID 40097388, 2025). "We observed enrichment of DEGs in pathways involved in type I IFN signaling during wt Mtb infection in both B6- and Il1r1-/—infected mouse groups, although they differed in their ability to control infection." (PMID 38603763, 2024). "Following infection of Il1r1−/− mice with Mtb HN878 smyc’::mCherry, the inhibitors were administered orally every other day, as depicted in schematics." (PMID 38853986, 2024). "Elevated expression levels of Fprs were observed at the mRNA level in Il1r1−/− mice at 25 days post-infection (dpi), compared to wild type (Wt) mouse lungs." (PMID 38853986, 2024). "Genes that overlapped with control-biased OCRs (regions with reduced accessibility due to MVA infection) included IL1R1, LFNG, and TTYH3 genes, all of which were downregulated in MVA-infected cells." (PMID 38862613, 2024). "In accordance with several earlier studies, we observed a reduction in the amount of virus-specific CD8 Teff cells that had infiltrated the lung parenchyma of full-body Il1r1−/− KO C57BL/6 mice compared with WT animals following infection with IAV." (PMID 37958758, 2023). "We also found that Nlrc4+/–Il1r1–/– mice largely phenocopy Nlrc4+/–Il1r1+/– mice and are resistant to infection." (PMID 36645406, 2023). "With the infection of larval E. granulosus, there were higher expression levels of many inflammatory factors in splenic B cells, such as Cxcl5, Il1r1, S100a8, S100a9, and CD14, which form a complex network of immune regulation." (PMID 35548052, 2022). "Another study by a different group showed that with 100 CFU Kurono strain aerosol infection Il1r1 KO mice had died after 45 days (KO mice had 3 logs more pulmonary CFU than WT at 35 days)." (PMID 34276708, 2021). "During another H37Rv strain infection (200 CFU i.n.), Il1r1 KO mice phenocopied Myd88 KO mice (died around 4 weeks post infection)." (PMID 34276708, 2021). "From a clinical viewpoint, our study also provides valuable insights identifying the NLRP3-IL-1β-IL-1R1 axis as potential targets for developing new drug therapies for preventing severe infection-elicited chronic inflammation and neurodegeneration." (PMID 32070376, 2020). "The course of the infection in IL-1R1 KO and WT mice was similar, and from day 5 onward both groups experienced acute weight loss and clinical disease." (PMID 32973802, 2020). "The only immune defect detected during this early phase of infection in IL-1R1 KO mice was a decrease in neutrophils recruited to the peritoneal cavity." (PMID 32703941, 2020). "We find IL-1R1 expression predominantly on blood vasculature in the brain, and observe IL-1-dependent activation of the vasculature during infection." (PMID 32703941, 2020).
infection (continued). "Accordingly, WT and Il1r1-/- mice had significantly different bacterial burdens at day 5 post-infection with this lower inoculum, even though bacterial burdens were roughly equivalent at the final time point (day 14)." (PMID 30978245, 2019). "In both WT and Il1r1-/- mice, the initial S. aureus inoculum of 105 CFUs replicates to approximately 107 CFUs by day 1 post-infection." (PMID 30978245, 2019). "At day 1 post-infection, WT and Il1r1-/- mice were found to have neutrophils comprising less than 10% of CD45+ cells in the bone marrow." (PMID 30978245, 2019). "By day 3 post-infection, Il1r1-/- mice have significantly fewer neutrophils in the infected bone marrow compared to WT mice." (PMID 30978245, 2019). "Neutrophil abundance at day 5 post-infection is comparable between WT and Il1r1-/- genotypes, but again was significantly decreased in Il1r1-/- femurs at day 14 post-infection." (PMID 30978245, 2019). "In contrast, bacterial burdens in Il1r1-/- mice were essentially unchanged through day 5 post-infection, and only declined between days 5 and 10 post-infection." (PMID 30978245, 2019). "To further demonstrate the direct involvement of pDCs for early IFN-α and IFN-β production, we depleted pDCs in Aim2−/−, Nlrp3−/−, Casp1−/−, and Il1r1−/− mice by injection of anti-mPDCA-1 antibody at 12 h before and 12 h after infection." (PMID 30470758, 2018). "We found that mPDCA-1-mediated depletion of pDCs in Aim2−/−, Nlrp3−/−, Casp1−/−, and Il1r1−/− mice markedly decreased serum levels of IFN-α/β at day 1 after YM infection, compared with those treated with control antibody." (PMID 30470758, 2018). "The levels of G-CSF in the serum and lung BALF of IL-1R1-/- mice were lower than that of WT mice during infection." (PMID 28585438, 2017). "Our work also indicated that IL-1R1-/- mice had less severe lung inflammation pathology than that of WT mice at the same early infection stage." (PMID 28585438, 2017). "In the previous work, the inflammatory lung pathology of WT mice was more severe than that of IL-1R1-/- mice at the early infection stage (3 dpi)." (PMID 28585438, 2017). "In IL-1R1-/- mice, however, the numbers of leukocytes were significantly lower than those of WT mice at every post-infection time point." (PMID 28585438, 2017). "Histological analysis revealed reduced lung inflammation during early infection but severe lung pathology in late infection in IL-1R1-/- mice compared with that in WT infected mice." (PMID 28585438, 2017). "The BALF lymphocytes increased following infection, and the numbers of lymphocytes in IL-1R1-/- mice were significantly lower than that in WT mice at the late stage of infection (5-8 dpi)." (PMID 28585438, 2017). "Decreased innate cellular influx into the airways of IL-1R1-/- mice was observed in the early infection period, which was primarily due to the significantly reduced neutrophil infiltration into the infected lungs, based on the BALF cell count." (PMID 28585438, 2017). "The lung wet-to-dry ratios of IL-1R1-/- mice were significantly higher than those of WT mice at 9 dpi, suggesting that the IL-1R1-/- mice suffered more severe lung edema during late infection." (PMID 28585438, 2017). "Analysis of total leukocyte numbers in the BALF of both WT and IL-1R1-/- mice showed that the number of leukocytes increased sharply during initial infection (2-5 dpi) and peaked at 5 dpi before decreasing gradually." (PMID 28585438, 2017). "Results showed that during infection, the numbers of neutrophils were significantly lower in IL-1R1-/- mice than in WT mice, whereas the numbers of macrophages and monocytes tended to be the same." (PMID 28585438, 2017). "In support of studies reporting increased susceptibility to infection with AUD, we report down-regulation of a number of genes important for host defense such as cytokines (IL1R1 and TNFSF11), chemokines (CCL2), and receptors (TGFBR1 and TLR8)." (PMID 27427759, 2016).
infection (continued). "In consequence Il1r1-/- mice were unable to control the fungus and displayed an increased fungal load in the tongue on day 3 post-infection." (PMID 27632536, 2016). "Mechanistically, we found impaired CXCL13 chemokine induction early after infection in Il1r1−/− mice." (PMID 27579026, 2016). "The chemokine CXCL12 is important for B cell lymphopoiesis, but expression of this chemokine was only slightly reduced early after infection in Il1r1−/− mice." (PMID 27579026, 2016). "NLRP3 activity was instead defective in Il1r1–/– mice, in which the attenuated IL-1β production was concomitant with a reduced disease severity during infections." (PMID 26972847, 2016). "During infection, binding of cytokine IL-1 to IL-1R1 enables transmigration and infiltration of inflammatory cells and over-activation leads to tissue damage." (PMID 26870992, 2016). "Pattern "Virulent", in contrast, includes 1,165 genes whose expression levels were less strongly changed after infection with heat-inactivated MTB H37Rv or the attenuated vaccine strain BCG compared to the other bacteria (e.g. IL1R1, IRF1, PILRB)." (PMID 26586179, 2015). "In support, the MHV-3 infection efficiency in IL-1R1-/- PEMs dropped more significantly than in the WT counterparts in vivo." (PMID 26367131, 2015). "This conclusion was also supported by the observation that Il-1r1-/- or Il-1b-/- mice appear to be able to control the infection, at least in its early stages, but eventually succumbed." (PMID 25768794, 2015). "Our data indicated that although IL-1R1 pathway is essential for controlling acute infection by virulent M. tuberculosis, presence of either IL-1α or IL-1β allowed to survive acute M. tuberculosis infection." (PMID 25400917, 2013). "Though both B6 and Il1r1−/− mice received similar initial bacterial burdens, Il1r1−/− mice show a defect in bacterial clearance as early as 24 hours post-infection." (PMID 23762026, 2013). "Il1r1−/− mice exhibited an identical course of infection as wild-type controls, consistent with previous studies." (PMID 23555256, 2013). "Mycobacterial burden was sharply elevated 72 hours after infection in the absence or presence of 1,25D when macrophages were co-cultured with IL1R1-depleted SAECs." (PMID 23762029, 2013). "Lung IFNγ levels were highly elevated in mice deficient for both IL-1α and IL-1β or for IL-1R1 at 5 weeks after M. tuberculosis infection, reminiscent of TNF deficient mice at 4 weeks, when they succumb to infection." (PMID 25400917, 2013). "These processes are driven by IL-1α and IL-1β which signal through the IL-1R1 (IL-1Rα) and MyD88 to drive downstream NF-κB activation and subsequent expression of genes whose products regulate the immune response to infection." (PMID 23209411, 2012). "In contrast, significantly lower amounts of bacteria were recovered 48 hours post infection from Il-1r1-/- mice compared to WT mice confirming their higher resistance." (PMID 22241982, 2011). "As IL-1β is produced in the cornea early after infection, it seems reasonable to assume that the MyD88 dependence is due to IL-1R1 signaling." (PMID 20617171, 2010). "In contrast, MyD88-dependent protection from lethal VSV infection occurred independent of type I interferon, correlated with the recruitment of monocytes to the site of infection and was dependent on IL-1R1 signaling." (PMID 19079579, 2008). "Although Tgfβrs, Il6ra, and Il1r1 were expressed on Th17 cells, it is likely that some of the IL-17-producing Th17 cells detected in this study were already differentiated and residing in the small intestine before infection." (PMID 40127923, 2025). "At this time point (48 h post-infection), there was already a considerably higher fungal load in the brains of Il1r1-/- mice, which could indicate that microglia and border-associated macrophages might be especially vulnerable and die due to infection." (PMID 40097388, 2025).
infection (continued). "Genes upregulated in the infected Il1r1-/- mice were highly overlapping between different kidney cell types, suggesting that in these mice, infection causes an upregulation of non-cell-specific gene programs." (PMID 40097388, 2025). "Since fungal titer in Il1r1-/- mice started to differ from WT mice already at 24 h p.i., we suspected that a crucial role of IL-1R signaling may be instigated very early after infection." (PMID 40097388, 2025). "Interestingly, we found co-localization of hypoxic regions and infection foci more in the Il1r1-/- mice than in the Il1r1+/- controls." (PMID 40097388, 2025). "A limitation of our experimental model is the use of full-body Il1r1−/− animals, from which we cannot deduct whether the experimental observations following infection were necessarily driven by direct IL-1 activity on CD8 T cells." (PMID 37958758, 2023). "Of importance, prolonged use of Anakinra (IL-1R1 antagonist) in patients has not been associated with increased infection rates." (PMID 35632584, 2022). "To investigate the contribution of this innate immune pathway to the prevention of mycobacterial cytosolic escape, we infected Il1r1−/− and B6 wild-type (WT) mice with M. tuberculosis and 4 weeks after infection fixed lung tissue and processed it for TEM analysis." (PMID 33952660, 2021). "This hypothesis is consistent with the observations that in the high-dose conidia model, IL-1R1-/- mice produced lower levels of G-CSF during infection and that CXCL1 supplementation only partially restored control of fungal growth." (PMID 34322116, 2021). "Our results demonstrate that this fluorescent strain can be used in conjunction with the mBD1−/− strain of mice to provide a useful method for testing the efficacy of all classes of antifungal agents in disseminated infections as well as with IL1r1−/− mice in mucosal models of infection." (PMID 33007818, 2020). "Notably, antiviral T-cell immunity was reduced eight days post infection following LCMV infection in Il1r1-/- compared to control animals." (PMID 33002089, 2020). "To test whether endothelial expression of IL-1R1 is required in this infection, we first assessed potential contributions from radiosensitive (hematopoietic) and radio-resistant (non-hematopoietic) cells." (PMID 32703941, 2020). "However, in line with the reduced antiviral response in the liver, we observed a significant increase in LCMV titers in the liver of Il1r1-/- mice as compared to wildtype controls eight days post infection in the liver." (PMID 33002089, 2020). "Notably, in the ctfr−/−, il1r1−/− d/d mouse model of PA infection, neutralization of IL-1β attenuated the infection and improved bacterial clearance." (PMID 31089134, 2019). "Importantly, these data do not completely control for differences in bacterial burdens at the site of infection, where Il1r1-/- mice harbor higher bacterial burdens at day 5 post-infection with a lower inocula." (PMID 30978245, 2019). "However, Il1r1-/- mice do equilibrate bacterial burdens to the same level at WT mice by day 14 post-infection." (PMID 30978245, 2019). "The significantly elevated expression of HGF, IL-1R1, and IL-6RA in female mice in group ET-EECP might be associated with limited pro-inflammatory effects and would be helpful in the clearance of infection caused by alcohol in the liver tissue." (PMID 31998465, 2019). "Excitingly, although Il1r1-/- mice harbored higher bacterial burdens throughout the course of infection, they did not exhibit trabecular bone loss or increased osteoclastogenesis relative to contralateral, uninfected femurs." (PMID 30978245, 2019). "To determine whether robust production of type I IFN in inflammasome-deficient mice contributed to dendritic cell maturation, we infected WT and Il1r1−/− mice with YM and then isolated splenocytes at day 4 post infection for mature DC population analysis." (PMID 30470758, 2018). "In medium-dose infection, Casp1−/− and Il1r1−/− mice were partially resistant." (PMID 30470758, 2018).